IL6 (interleukin 6)
Diseases named in the same sentence as IL6 in open-access papers (continued):
Sharing a sentence is not in itself a finding about the gene and the disease.
infectious disease (continued). "The WBC count is controlled by cytokines, especially interleukin-6 and interleukin-8, and WBCs play a major role in inflammatory processes and in defending the body against infectious disorders." (PMID 22853735, 2012). "IL-6, secreted by various cells including T lymphocytes, fibroblasts, B lymphocytes, and monocytes/macrophages, plays a critical role in inflammatory and immune responses, serving as an important marker for early diagnosis and warning of infectious diseases." (PMID 41234411, 2025). "In infectious diseases, IL6 levels are usually elevated, reflecting the severity of the disease." (PMID 40144526, 2025). "The severity of the disease as well as concomitant factors such as infectious diseases may influence the rise in IL-6 levels." (PMID 39941070, 2025). "The dysregulation of IL-6 cytokines has been found in various infectious diseases." (PMID 38251210, 2024). "IL-6 has already been reported to positively correlate with infectious disease severity." (PMID 37918965, 2024). "Since IL-6 is involved in different biological processes including immune regulation, hematopoiesis, tissue repair, inflammation, oncogenesis, metabolic control, and sleep, it has a pivotal role in acute, chronic, and communicable diseases." (PMID 37754132, 2023). "IL-6 pathways have been reported to modulate the expression of IL6 and IL6R genes, respectively, and to be associated with a number of inflammatory, autoimmune, and infectious diseases." (PMID 37243282, 2023). "Confounding conditions, such as undiagnosed infectious diseases or unknown drug interaction, could potentially have affected plasma levels of IL6 and IL6sR." (PMID 34023914, 2022). "TNF-α and IL-6 are common inflammatory factors, and their blood levels show corresponding changes when inflammation occurs, and increases in its levels can be seen in various infectious diseases and have significant signs of illness in HP-infected patients." (PMID 35414799, 2022). "Many studies have shown that IL-6 and IL-10 are related to infectious disease." (PMID 35432366, 2022). "Research has shown that IL-6, which is abundant in the serum of patients got some infectious diseases, may downregulate NKG2D on NK cells, leading to impaired NK activity." (PMID 34568032, 2021). "However, the diagnostic properties of suPAR compared to C-reactive protein (CRP) and interleukin-6 (IL-6) are weak in infectious diseases." (PMID 34384460, 2021). "IL-6 is a pleiotropic cytokine which can control immune regulation in infectious diseases." (PMID 32934336, 2020). "In Cyld−/− mice, both increased NF-κB-dependent IL-6 production and K63-ubiquitination of STAT3 contribute to the enhanced STAT3 activity, which further illustrates the central importance of IL-6/gp130-dependent STAT3 activity for protective host responses in infectious diseases." (PMID 23825949, 2013). "However, the concentration of IL-6 also increases in patients with other non-infectious diseases." (PMID 34630395, 2021). "Therefore, adoptive Treg therapy using genetically-engineered Tregs with enhanced stability in the presence of pro-inflammatory IL-6 environments could be a promising treatment in the context of autoimmune and infectious diseases." (PMID 34408743, 2021). "As the main reason for tooth loss, oral bacterial infectious diseases are associated with a chronic low-grade inflammation, which can upregulate inflammatory biomarkers including C-reactive protein (CRP), tumor necrosis factor alpha (TNF-alpha), and interleukin-6 (IL-6)." (PMID 32649678, 2020). "In the LPS-induced infectious disease model, there was a significant increase in chemokines (CCL2), proinflammatory cytokines (IL1β, IL6, TNFα), and a marked decrease in MCH." (PMID 38654385, 2024). "Many inflammatory biomarkers including CRP, Cytokines i.e. Tumor necrosis factors (TNF), interleukin-6 (IL-6) and ESR aid in diagnosis of complex inflammatory and infectious disorders but lack specificity." (PMID 38681106, 2024).
infectious disease (continued). "Inflammatory cytokines, such as interleukin-1 (IL-1), interleukin-6 (IL-6), and tumor necrosis factor-alpha (TNF-α), play a significant role in the pathogenesis of infectious diseases." (PMID 38305363, 2024). "Some researchers believe that simultaneous detection of IL-6, CRP and procalcitonin can improve the detection rate of early inflammation in the event of inflammation or infectious diseases." (PMID 37442959, 2023). "It is also useful for prevention of septic infection, while anti‐IL‐6 antibody and TNF‐α blocker sometimes aggravate infectious diseases because of oversuppression of the immune system." (PMID 35588199, 2022). "Although the LOD of IL-6 is higher than fluorescence immunoassay and ECL immunoassay, it still meets the requirements of diagnosing infectious diseases." (PMID 35144683, 2022). "Previous studies demonstrated that SOCS3-mediated IL-6/STAT3 signaling pathway regulates multiple cytokine signaling pathways in autoimmune and infectious diseases." (PMID 34147072, 2021). "Increase in plasma pro-inflammatory cytokines such as interleukin 6 (IL-6), interleukin 8 (IL-8) and TNF- α during infectious disease, correlating with increased ROS levels, also suggests that an oxidative mechanism is involved in the immune response." (PMID 34123871, 2021). "It is also useful for prevention of septic infection, while anti-IL-6 antibody and TNF-α blocker sometimes aggravate infectious diseases." (PMID 29699567, 2018). "Addressing these limitations through more extensive prospective studies with standardized methodologies and comprehensive data collection protocols will be crucial for advancing our understanding of the utility of arachidonic acid, IL-6, and CRP as biomarkers in infectious diseases." (PMID 39066228, 2024). "Recently, we demonstrated that in vitro exposure of peripheral blood cells from healthy donors to SARS-CoV-2 spike protein induced an early expression of HERV-W, preceding the induction of IL-6, suggesting a role for HERV activation in the inflammation process related to infectious diseases." (PMID 36430402, 2022). "In order to show that EVs from GES-1 infected with H. pylori cells participate in the spread of infectious disease, the mRNA levels of proinflammatory cytokines TNF-α, IL-8, IL-6, IL-1β and IL-23, in GES-1 and AGS cells stimulated for 24 h with EVHp- or EVHp+ were measured by RT-qPCR." (PMID 36313672, 2022). "In human infectious diseases, GZMK can activate the protease activated receptor-1 (PAR-1) in endothelial cells and induce the production of inflammatory cytokines (TNF-α, IL-1, and IL-6)." (PMID 36199375, 2022). "We also did not consider potential adverse effects of perturbing IL-6 signaling, including implications for allergic, autoimmune and infectious disease." (PMID 35948913, 2022). "In spite of the pathological role of IL-6 and TNF-α in chronic inflammatory diseases, the anti-inflammatory contribution of IL-6 to the resolution of infectious disease through mitigation of damage to the lung architecture, and reduction of proinflammatory cytokine production is clear." (PMID 33680987, 2021). "Furthermore, following infectious disease, LITAF, IL-6, and IFN-γ production can impair the intestinal tight junction barrier." (PMID 34944274, 2021). "Also, the action of vitamin C in the inhibition of IL-6 and TNF-α is significant in terms of inflammatory and infectious disease management." (PMID 34812049, 2021). "Moreover, further infectious diseases such as influenza A (H1N1) can be addressed, where pH in lysosomes, IL-6, and lysosomal sphingolipid metabolism play a crucial role." (PMID 33670304, 2021). "CRP, IL-6, and PCT are commonly used for the diagnosis of various infectious diseases." (PMID 32851063, 2020).
infectious disease (continued). "Moreover, in vitro exposure of PBMCs from healthy donors to SARS-CoV-2 Spike protein induced an early expression of HERV-W ENV, and ahead of the induction of IL-6, suggesting early HERV activation consistent with its potential role in the inflammation process related to infectious diseases." (PMID 36451209, 2022). "Moreover, in human infectious diseases, GZMK has been found to activate protease-activated receptor-1 (PAR-1) in endothelial and fibroblast cells and induce the production of inflammatory cytokines, such as TNF-α, IL1, IL-6, and MCP-1." (PMID 34603038, 2021). "White blood cells, lymphocytes and elevated levels of IL-2, IL-4, and IL-6 were also noticed in the mice in CpG-CNP group, indicating that CpG-CNP can serve as an effective adjuvant in order to improve the immune protection and resistance of porcine against infectious diseases." (PMID 32316990, 2020). "Herbal medicine probably controls the infectious disease mainly based on immunomodulatory agents stimulation (such as GSK3B, MAPK14, PPARγ) will probably help innate and adaptive immune, and regulation the inflammatory cytokines and proinflammatory mediators (like IL-6, IL-8, TNF-α, COX2)." (PMID 29301573, 2018). "In conclusion, we conclude that 7 days of weight loss programs undertaken in preparation for competition might degrade immune functions and conduct to the appearance of infectious diseases such as URTI symptoms in male judo athletes by the increase of proinflammatory cytokines (i.e., IL-6; TNF-α)." (PMID 26075039, 2015). "However, despite numerous preclinical and clinical studies that aim to develop TLR agonists into drugs for the treatment of infectious diseases, the effect of TLR induced IL-6 on virus-specific CD8+ T cell responses remains largely unknown." (PMID 25994622, 2015). "Taken together, TLR ligand induced IL-6 counter-regulates effector T cell responses in vivo and thus a combination therapy of TLR stimulation and IL-6 blockade may be an effective new approach for the therapy of infectious diseases." (PMID 25994622, 2015). "Furthermore, the detection of an IL-10-to-IL-6 ratio greater than 1 in the vitreous and greater than 0.72 in the cerebrospinal fluid is considered useful for differentiating between PVRL and intraocular infectious diseases, and PCNL from intracranial infections, respectively." (PMID 33146828, 2021). "Thus, type I IFNs should be added to the long list of cytokines (IL-1β, IL-4, IL-6, IL-15, IL-21) and members of the tumor necrosis factor superfamily (TNFSF) (GITR-L, 4-1BB-L, OX40-L and TNF-α) that are purported to decrease Treg suppressive function in autoimmune and infectious disease models." (PMID 29672594, 2018).
psychiatric disorder (153 papers, 2010 to 2026). A disorder characterized by behavioral and/or psychological abnormalities, often accompanied by physical symptoms. "Altogether, these studies show that changes in the three core behavioral domains associated with several psychiatric disorders can be detected early in pre-pubescent mice following a transient developmental increase in IL-6." (PMID 39984136, 2025). "In the brain, chronic and dysregulated expression of IL-6 is implicated in the disease progression of a range of neurological and psychiatric disorders." (PMID 39931547, 2025). "Particularly noteworthy is the existence of a close relationship between ROS and IL-6 in microglial cells, since both factors are suggested to be implicated in neurodegenerative and psychiatric disorders." (PMID 39652148, 2025). "The risk of neurological and psychiatric disorders increases in the offspring of mothers with greater levels of IL-6 during pregnancy." (PMID 39109071, 2024). "Previous studies have typically assessed only serum measures of CRP and IL-6 to investigate the associations between inflammation and psychiatric disorders." (PMID 36277463, 2022). "Several inflammation cytokines, such as TNF and IL-6 in serum, have been considered as sensitive biomarkers in identifying a predisposition for psychiatric disorder or as a diagnosis of a psychiatric disorder." (PMID 34394017, 2021). "Chronically elevated inflammation in the development of psychiatric symptoms is supported by data from Whitehall II study showing repeated measurements of IL-6 dose-dependently increasing the risk of future common mental disorder." (PMID 26631274, 2016). "An MR study investigating the effect of peripheral inflammatory markers on brain structure in older adults from UK Biobank found potential causal mechanisms for serum IL-6 on regions associated with major psychiatric disorders (temporal, fusiform and frontal cortices)." (PMID 39865800, 2025). "One longitudinal study has shown that psychosocial stress at an early age (9 years) is related to high levels of IL-6 and C reactive protein in serum, which was considered a risk factor for the development of psychiatric disorders such as depression and psychotic events in adulthood (18 years)." (PMID 39796167, 2025). "Hence, there appears to be a role for astrocytes in the neuroinflammation associated with psychiatric disorders, which is relevant to the altered IL-6 and inflammatory signaling in BDI patient astrocytes." (PMID 38175142, 2024). "Serum concentrations of pro-inflammatory factors, such as IFN-α, IL-6, and IL-8, may serve as potential markers of psychiatric disorders, as inflammation in the CNS is associated with neurodegeneration." (PMID 38807424, 2024). "One reason may be that the SARS-CoV-2 increases the risk of psychiatric disorders in patients by increasing the levels of inflammatory factors, such as interleukin-6 (IL-6) and interleukin-8 (IL-8), in the blood and cerebrospinal fluid." (PMID 37867774, 2023). "Moreover, specific probiotics have been found to reduce the levels of pro-inflammatory cytokines including TNF-α, IL-1, or IL-6 often associated with certain psychiatric disorders." (PMID 36133749, 2022). "Additionally, higher levels of IL-6 in childhood are associated with increased risk of psychiatric disorders in adulthood." (PMID 36225733, 2022). "Furthermore, LcS significantly decreased the IL-6 levels and regulated the intestinal microbiota associated with mental illness." (PMID 34209804, 2021). "Collectively these data suggest a potential pathophysiological involvement of the pro-inflammatory cytokine IL-6 in the circadian alterations associated with severe neurological and psychiatric disorders and invite further investigations on the underlying molecular mechanisms." (PMID 28382017, 2017).
psychiatric disorder (continued). "Tolerance mechanisms appear to be impaired relatively frequently in the central nervous system (CNS) because many neurological and psychiatric diseases are associated with excessive inflammation, exemplified by elevated levels of the pro-inflammatory cytokine interleukin-6 (IL-6)." (PMID 22022450, 2011). "Future Directions: The integration of psychiatric scales (e.g., PHQ-9, GAD-7) with inflammatory biomarkers (CRP, IL-6) could improve diagnostic specificity, enabling differentiation between primary psychiatric disorders and inflammation-driven secondary conditions." (PMID 40218134, 2025). "Thus, an increase in CSF IL‐6 may play an important causal role across different psychiatric disorders." (PMID 39317977, 2024). "Additionally, a recent MR study suggests that IL-6 may have causal effects on brain structures relevant to psychiatric disorders." (PMID 36277463, 2022). "In conclusion, adolescent psychiatric disorder diagnoses were associated with elevated levels of MMP-9, IL-6, and CRP and with inhibitory control dysfunction." (PMID 40219625, 2025). "The activation of inflammatory cytokines such as interleukin-6 (IL-6) and tumor necrosis factor-alpha (TNF-α) has been implicated in both mental illnesses and metabolic disturbances." (PMID 40376339, 2025). "IL-6 contributes to the pathogenesis of psychiatric disorders by influencing the hypothalamic-pituitary-adrenal (HPA) axis, altering the metabolism of monoamine neurotransmitters, and promoting neuroinflammatory processes." (PMID 40708589, 2025). "In the present study, we initially examined the effects of NS on IL-6 and TNF-α levels, owing to the strong association between these cytokines and mental illness." (PMID 38339101, 2024). "We found that CSF IL‐6 levels were significantly correlated with trait anxiety and autonomy frustration in patients with psychiatric disorders." (PMID 39317977, 2024). "This is consistent with a view that IL-6 pathways are likely to be involved at different stages of the pathogenesis of psychiatric disorders." (PMID 36781081, 2023). "C-reactive protein (CRP), tumor necrosis factor (TNF), soluble TNF receptor 1 (sTNFR1) and interleukin-6 (IL-6) are among the most frequently investigated inflammatory markers in the field of severe mental illness and exercise research." (PMID 37265560, 2023). "Several reports have shown that blockade of IL-6 signaling (for example, through anti-IL-6 receptor antibody) can be a potential therapeutic strategy for psychiatric disorders." (PMID 36034871, 2022). "Expression of IL-6 in CNS in physiological conditions remains at a low level but elevated levels are reported in several neurodegenerative or psychiatric disease as well as in CNS infection and injury." (PMID 35286352, 2022). "Multiple researches have highlighted IL-6 as the most predominant cytokine inducible upon stress and it plays a cardinal role in psychiatric disorders." (PMID 36183107, 2022). "Treatment with therapeutic drugs for psychiatric disorders reduces blood IL-6 and corticosterone levels, increases BDNF expression, and alleviates neuropsychiatric disorders." (PMID 32158447, 2020). "High baseline serum interleukin 6 concentrations, being female, history of psychiatric disorder, sub-threshold depressive symptoms, and low educational level significantly predicted the occurrence of MDD during antiviral treatment." (PMID 23550100, 2013). "Under physiological conditions, IL-6 is present at low levels; however, its expression markedly increases during infections, injuries, and neurodegenerative or psychiatric disorders, implicating IL-6 in the regulation of hippocampus-dependent synaptic plasticity and memory." (PMID 41292555, 2025). "Future work adapting the present methodology may clarify the contribution of monocytes and other cell types to IL-6 production across specific psychiatric disorders." (PMID 41450979, 2025).